TNF (tumor necrosis factor)
Diseases named in the same sentence as TNF in open-access papers (continued):
Sharing a sentence is not in itself a finding about the gene and the disease.
glaucoma (continued). "In human patients with glaucoma, TNFα and TNFα receptor 1 were upregulated compared with age-matched normal donors." (PMID 32031578, 2020). "The secretion of TNF by microglial cells was shown to contribute to RGC degeneration as its receptor is highly increased in glaucoma in RGCs, astrocytes, microglia and Müller cells, triggering a cascade of events that culminates in RGC demise." (PMID 32218163, 2020). "The inflammatory changes related to the disease were correlated with a rise of TNFα in glaucoma patients as well as in experimental models of glaucoma." (PMID 32106630, 2020). "Higher levels of TNF-α were detected in aqueous humour of patients with glaucoma compared to controls." (PMID 32774906, 2020). "FasL, a type II transmembrane protein of the TNF group, promotes apoptosis after binding to the Fas receptor and is involved in the pathogenesis of glaucoma also through inflammatory pathways." (PMID 33613418, 2020). "Using the microbead-induced ocular hypertension mouse model of glaucoma, we show that microglia and infiltrating macrophages upregulate C1q, TNF-α, and IL-1α." (PMID 33147455, 2020). "Oxidative stress also can enhance production of several cytokines, including interleukins, interferon-gamma, and tumor necrosis factor alpha, which contributes to the axonal injury in glaucoma, and the excess production of exfoliative material." (PMID 33352680, 2020). "Several studies using ELISA and single-plex bead immunoassay techniques have shown increases in TNF-α in the AH of glaucoma patients when compared to controls." (PMID 30673862, 2019). "In human and experimental models of glaucoma, activated microglia are detected in the optic nerve head and retina, and blocking microglia activation with minocycline, anti-TNF, or irradiation prevents death of RGCs and axon degeneration." (PMID 31570110, 2019). "The link between tumor necrosis factor-α (TNFα) and retinal ganglion cell (RGC) loss in glaucoma and traumatic optic neuropathies has been extensively investigated in humans and animal models." (PMID 31680831, 2019). "Many of the cytokines with increased expression measurements in our study (IL-1α, IL-1β, IL-6, TNF-α, FasL) were already described as being elevated in glaucoma patients." (PMID 30967499, 2019). "The involvement of TNFα gene and protein alteration in retina has been reported in animal model of glaucoma and human primary open angle glaucoma." (PMID 30524222, 2018). "Strikingly, these MMP-2 null mice showed reduced levels of TNF, a proinflammatory cytokine with a well-documented neurodegeneration-exacerbating function in glaucoma." (PMID 26451076, 2015). "We have recently demonstrated that the activation of autophagy leads to axonal protection in the hypertensive experimental glaucoma model and in the tumor necrosis factor (TNF)-induced optic nerve degeneration model." (PMID 26578885, 2015). "Glaucoma is a complex disease and numerous retina proteins have been demonstrated to be up-regulated during the pathogenesis of glaucoma, including TNF-α, TNF-R1, various protein kinases, glial cell activation, and proteolytic caspases." (PMID 24586745, 2014). "Microglial activation and microglia-derived neurotoxic mediators, including TNF-α, NO and ROS, have been shown to play detrimental roles in neuron death and glaucoma." (PMID 24923557, 2014). "Neurotoxic mediators, including reactive oxygen species (ROS), NO and TNF-α, have been implicated in secondary waves of RGC apoptosis in glaucoma." (PMID 24923557, 2014). "For example, increased levels of cytokines including interferon (IFN)- γ, interleukins (ILs), and tumor necrosis factor (TNF)- α have been reported to be associated with RGC death in numerous retinopathies including glaucoma." (PMID 24586745, 2014). "Five studies in which the TNF-α levels in AH between patients with glaucoma and control subjects were compared were retrieved." (PMID 23559847, 2013).
glaucoma (continued). "We also observed comparable trends for pro-inflammatory regulations in glaucomatous retinal tissues in our study like elevated concentrations of TNF-α (p = 0.13), IL-1β (p = 0.08), IL-6 (p = 0.26) and IL-8 (p = 0.04) compared to non-glaucoma controls." (PMID 23451242, 2013). "We also performed a meta-analysis to compare the TNF-α level in AH between patients with glaucoma and the control subjects." (PMID 23559847, 2013). "Other studies showed that patients with glaucoma were more likely to have detectable levels of TNF-α in their AH." (PMID 23559847, 2013). "Using a mouse model of glaucoma, we previously found that TNF-α mediates the cytotoxic effect of ocular hypertension (OHT) on RGCs through a mechanism that involves microglial activation and loss of oligodendrocytes." (PMID 22802951, 2012). "Optineurin protein might play a role in the protection of the optic nerve from tumor necrosis factor-mediated apoptosis, and mutations in optineurin could lead to loss of function of this protein, which could decrease the threshold for ganglion cell apoptosis in patients with glaucoma." (PMID 22509109, 2012). "The dopaminergic agent, GLC756, has recently been shown to inhibit TNF-α release from activated rat mast cells, suggesting a potential role for glaucoma neuroprotection." (PMID 22737394, 2012). "TNF-α and its receptor (TNF-R1) m RNA were increased in the retina of glaucoma patients, while anti TNF-α antibodies can prevent ganglion cell death in a mouse model of glaucoma." (PMID 23157966, 2012). "A recent study has shown that a significantly higher percentage of patients in the glaucoma group were positive for TNF in the aqueous humor compared with the cataract group." (PMID 23316132, 2012). "More recently, a study of proteomic data from human glaucoma has shown a prominent upregulation of TNF/TNF receptor 1 signaling in the glaucomatous retina." (PMID 23316132, 2012). "The present results, supported by considerable evidence from other studies, suggest that Etanercept or other TNF- α antagonists or suppressors of inflammation should be considered as an adjunct therapy in the treatment of glaucoma." (PMID 22802951, 2012). "Other evidence showed that anti- TNF-α antibodies can prevent death of retinal ganglion cells (RGCs) by reducing ocular hypertension, which indicates that reducing the expression of TNF-α would be beneficial in treating glaucoma." (PMID 22509108, 2012). "Recent laboratory evidence indicates that TNF-α have either protective or adverse effects on primary open angle glaucoma (POAG)." (PMID 22509108, 2012). "Elevated levels of TNFα have been detected in the aqueous humor and retinal layers of glaucoma patients with primary open angle, normal tension, and exfoliation glaucoma." (PMID 21479271, 2011). "Development of glaucoma also coincided with increased levels of TNFα and TNFα-inducible genes in laser induced rodent models of elevated IOP." (PMID 21479271, 2011). "We have compared the ability of these mice to develop RGC degeneration following intraocular TNFα treatment and in a spontaneous model of glaucoma." (PMID 21479271, 2011). "Our molecular findings, in accord with previously published studies, suggest that modulation of TNF alpha and its receptors is correlated to the development of glaucoma." (PMID 21042562, 2010). "TNF G/A genotype was also found to be lower in our PEX glaucoma patients than in control subjects, we detected a high prevalence of the G/G genotype in Turkish PEX glaucoma patients." (PMID 18852869, 2008). "Lyso-PAF may be converted into PAF, indirectly prompting cells to release TNF-α and participating in the inflammatory process of glaucoma." (PMID 40486511, 2025). "However, in prolonged glaucoma pathology, uncontrolled microglial activation leads to the release of neurotoxic pro-inflammatory cytokines, including TNF-α, IL-6, and IL-1β, exacerbating neurodegeneration." (PMID 40457155, 2025).
glaucoma (continued). "TNF-α could transmit ROS from neuronal cells to vascular cells and also elicit NOX2-dependent ROS production in microglia and is detected in the atrial fluid of glaucoma patients with TNF-α." (PMID 38649885, 2024). "Those associations are supported by previous studies showing that increased expression of TNF and TNF receptors were observed in RGCs and the optic nerve head of patients with glaucoma and that TNF-mediated cell death is involved in the neurodegeneration process of glaucoma." (PMID 38598101, 2024). "In serum samples of glaucoma patients, increased levels of tumor necrosis factor-α (TNF-α) could be detected." (PMID 38515755, 2024). "This could support prior research that suggests TNF-α serum levels as a possible disease marker for glaucoma patients." (PMID 38515755, 2024). "Interestingly, increased retinal mRNA as well as serum levels of the tumor necrosis factor α were found throughout the different glaucoma groups." (PMID 38515755, 2024). "Previous studies indicate that TNF-α is upregulated in the retinas of individuals with glaucoma." (PMID 39408817, 2024). "There have been several recent reports showing a close relationship between TNF and glaucoma." (PMID 38598101, 2024). "accumulated data from several of our studies, combined with the present paper, suggest that corneal injuries, including surgery, might benefit from routine administration of anti-TNF-α biologics to reduce inflammation and future secondary glaucoma." (PMID 37803488, 2024). "Using a neuroinflammatory mouse model of glaucoma induced by the injection of TNF-α (tumor necrosis factor α), Ko and others (2020) showed that SARM1 is required for the loss of RGC axons and oligodendrocytes in optic nerves and axon degeneration in sensory neurons." (PMID 37002660, 2024). "Interestingly, TNFα upregulation has been implicated in RGC apoptosis in human glaucomatous ONH and in animal glaucoma models." (PMID 37566048, 2023). "ONH astrocytes from glaucoma patients also show higher production of nitric oxide (NO) and tumor necrosis factor (TNFα), which may damage retinal ganglion cells (RGCs)." (PMID 36769067, 2023). "Certainly, a better understanding of the role of TNF may allow us to the develop better treatments for glaucoma in terms of retinal protection." (PMID 37242611, 2023). "In addition, high levels of TNF-α in the aqueous humor have been associated with POAG, and its potential as a biomarker for glaucoma diagnoses or progression has been suggested." (PMID 37511830, 2023). "It has been shown that activation of the ephrinB1/EphB1 positive signaling pathway induces TNF-α production and may play an important role in the apoptosis of retinal ganglion cells in glaucoma." (PMID 37501725, 2023). "PB levels of TNF-α correlate with the severity of visual defects in glaucoma patients." (PMID 37020269, 2023). "A considerable amount of evidence recognizes TNFα as one of the most important players in glaucoma, even though its exact role in the disease progression remains unclear." (PMID 37242611, 2023). "The upregulation of the major proinflammatory cytokine TNF-α is well-known in glaucoma." (PMID 36837806, 2023). "Inappropriate TNF-α production or prolonged activation of TNF-α signaling can predispose to a broad spectrum of inflammatory diseases, including retinal disorders such as glaucoma or DR." (PMID 36936905, 2023). "Up-regulated TNFα expression was observed in Müller cells in the retina of glaucoma patients." (PMID 36769067, 2023). "Glaucoma patients in our study had end-stage, blind eyes with severe retinal atrophy and optic nerve head cupping on histopathology, possibly resulting in higher TNFα levels than reported in humans." (PMID 35998207, 2022). "Elevated TNF-α levels have been previously reported in glaucoma." (PMID 36079162, 2022).
glaucoma (continued). "Since TNF-α is secreted from activated glial cells in response to intraocular stress such as high pressure or ischemia, glaucoma patients with elevated TNF-α levels may show different clinical characteristics." (PMID 36079162, 2022). "IOP factors and vascular factors, including blood pressure and presence of central scotoma, may indicate glaucoma pathogenesis related to TNF-α elevation in OAG patients." (PMID 36079162, 2022). "In the NMDA-induced excitotoxic glaucoma model, microglia were activated and the release of TNFα from activated microglia may spread around RGCs and activate the TNFR1 of RGCs, leading to RIP1/RIP3/MLKL pathway activation and following RGCs necroptosis." (PMID 36289519, 2022). "It was found that Ba alleviates the expression of pro-inflammatory cytokines including TNF-α, IL-6, and IL-1β in mouse microglia, supporting its biomedical significance for glaucoma treatment as elevated levels of TNF-α, IL-6, and IL-1β are observed in the TM of glaucoma patients." (PMID 35806375, 2022). "In addition, minocycline or antibodies directed against tumour necrosis factor-alpha (TNF-α) can be used to block microglial activation in experimental glaucoma models, prevent immune cell infiltration, and significantly reduce RGC death." (PMID 36741384, 2022). "Although several studies documented contradicting role of TNFR1 and TNFR2 in glaucoma, TNF and its receptor may still serve as attractive targets in glaucoma therapy." (PMID 35651608, 2022). "Additionally, dogs with glaucoma had higher levels of IL-18 and TNFα in AH compared to dogs with anterior uveitis and POH following phacoemulsification." (PMID 35998207, 2022). "As a pleiotropic cytokine, the regulation and role of TNF in glaucoma are also varied." (PMID 35651608, 2022). "This understanding of the TNF-α expression pathway caused by glaucoma stimulation in Müller cells, and the reduction in TNF-α expression by statins, suggest statins as potential therapeutic agents for glaucoma treatment." (PMID 35563594, 2022). "In our experimental glaucoma model, molecules released by reactive macroglia such as TNF-α and IL-1β could induce the secondary death of RGCs." (PMID 35625676, 2022). "Interestingly, AH levels of IL-18 and TNFα were higher in glaucoma eyes than POH eyes following phacoemulsification surgery." (PMID 35998207, 2022). "Throughout literature, there is currently a lack of consensus on the functional outcomes of TNF/TNFRs signaling in glaucoma, resulting in conflicting reports and suggesting a dire need to investigate the cellular and molecular mechanisms that govern TNF pathways." (PMID 35651608, 2022). "TNF-α was also increased in the retinas of glaucoma patients." (PMID 35563594, 2022). "Moreover, they found that intravitreal TNF-α injection induced RGC death that mimics that the glaucoma, and blockade of microglial activation rescued this RGC death induced by TNF-α." (PMID 35844208, 2022). "For instance, TNFR1 antagonist only inhibits the function of TNF via TNFR1 without inhibiting host defense function via TNFR2 as complete inhibition of TNF in neurodegenerative diseases such as glaucoma may be contraindicative." (PMID 35651608, 2022). "Similarly, TrkC.T1 knockout (KO) and TrkC inhibition increased retinal ganglion cell survival in a mouse model of glaucoma by reducing TNFα production, implying that TrkC.T1 is upstream of TNFα." (PMID 36389729, 2022). "Therefore, this study provides evidence that TRPV4 is closely related to glaucoma pathophysiology through Müller gliosis and TNF-α production." (PMID 35563594, 2022). "In glaucoma mouse models, TNF-α levels were elevated in the retina with retinal ganglion cell loss." (PMID 36079162, 2022). "This may reveal glaucoma patients who may have neuroinflammation and TNF-α related cell deaths as a pathogenesis of glaucomatous damage." (PMID 36079162, 2022).
glaucoma (continued). "A considerable amount of empirical evidence has shown the significant association between tumor necrosis factor cytokine (TNF; TNFα) and glaucoma; however, the exact role of TNF in glaucoma progression remains unclear." (PMID 35651608, 2022). "TNF-α can be utilized as a predictor of the outcomes of glaucoma surgery." (PMID 34575451, 2021). "TNF-α also plays important roles in the pathogenesis of retinal diseases, such as glaucoma." (PMID 34419081, 2021). "Instead, a non-canonical form of necroptosis has recently been implicated in TNFα-induced SARM1/NAD-dependent axon neurodegeneration in glaucoma." (PMID 34199494, 2021). "Astroglial activation in glaucoma has been shown to increase the expression of many factors, including endothelin-1 (ET-1), tumor necrosis factor-α (TNF-α), oxidative stress molecules, and trophic factors, e.g., CNTF, with varied neuroprotective and harmful properties." (PMID 33796062, 2021). "While IL1B and IL6 may be associated with the risk of glaucoma, GPX and TNF may affect the glaucoma phenotype." (PMID 33803434, 2021). "In rodent glaucoma models, where mice were exposed to either hypoxic damage or ocular hypertension, a release of TNF-α and IL-1β from activated microglia accompanied by apoptosis of RGCs was found, supporting the involvement of microglia in glaucomatous neurodegeneration." (PMID 33796062, 2021). "Even though the role of OMT in glaucoma retardation has yet to be reported, we here report, for the first time, that OMT may retard the development and the progression of glaucoma by acting on targets such as TGFβ and TNFα." (PMID 35252223, 2021). "In this context, suppression of TNF-α, with an anti-TNF-α blocking antibody or the deletion of the gene encoding TNF-α, was shown to elicit neuroprotective effects in the optic nerve and RGCs in a mouse model of glaucoma." (PMID 33796062, 2021). "For example, Etanercept, a TNFα inhibitor widely used to control chronic inflammatory diseases such as rheumatoid arthritis, prevents approximately 50% of RGC loss in a rat model of glaucoma." (PMID 34440742, 2021). "The evidence suggests that TNF-α-induced RGC death in glaucoma could be mediated by multiple pathways." (PMID 34789280, 2021). "In advanced glaucoma, inflammatory mediators, including TNF-α, are increased." (PMID 33796062, 2021). "Therefore, these authors emphasized the possibility of using TNF-α as a biomarker in the early diagnosis of glaucoma and assessment of the severity of the disease." (PMID 34830671, 2021). "Quantifying IL-2 and TNF-α in glaucoma patients may additionally help monitor disease progression and the efficacy of therapy." (PMID 35052396, 2021). "Moreover, high levels of TNFα were also found in the retinas as well as in the optic nerve astrocytes and microglia in glaucoma patients." (PMID 32106630, 2020). "Thus, the coexistence of a rise in TNFα expression and inflammatory changes clearly implicates TNFα in the pathogenesis of RGC loss in glaucoma." (PMID 32106630, 2020). "The development of inflammation in AMD, diabetic retinopathy, retinitis pigmentosa, retinopathy of prematurity, and glaucoma seems to be regulated by interleukin-1 (IL-1) family members, as well as tumor necrosis factor alpha (TNF-α) and its counterpart interleukin-10 (IL-10)." (PMID 31973128, 2020). "In addition, higher levels of TNFα were found in the serum of patients with severe glaucoma compared to healthy subjects." (PMID 32106630, 2020). "Based on their experimental results, the investigators concluded that blocking TNF-α signaling or inflammation may be someday proven helpful in treating glaucoma." (PMID 33014446, 2020). "More and more studies suggest that TNFα plays an important role in glaucoma disease." (PMID 32106630, 2020).